ELF3 (E74 like ETS transcription factor 3)
Diseases named in the same sentence as ELF3 in open-access papers (continued):
Sharing a sentence is not in itself a finding about the gene and the disease.
ovarian carcinoma (continued). "We observed strong nuclear ELF3 expression in ovarian cancer epithelia by immunostaining." (PMID 28199976, 2017). "Based on the transcriptome analysis, we hypothesize that ELF3 is a favorable prognostic marker for ovarian cancer and its expression suppresses cancer progression." (PMID 28199976, 2017). "We evaluated ELF3 expression in 10 ovarian cancer cell lines using Western blot analysis." (PMID 28199976, 2017). "In conclusion, ELF3 is a favorable prognostic marker for ovarian cancer." (PMID 28199976, 2017). "In addition, animals injected with ELF3-overexpressing cancer cells had significantly lower tumor weights (p < 0.001) and ascites volumes (p < 0.001) than did the control animals, further supporting the tumor-inhibitory roles of ELF3 regarding ovarian cancer." (PMID 28199976, 2017). "Similarly, ELF3 overexpression in ovarian cancer cells reduced their sensitivity to cisplatin." (PMID 36864480, 2023). "Similarly, ELF3 correlated with an epithelial phenotype in ovarian cancer cells, and its overexpression in SKOV3 cells reduced invasion and led to a downregulation of mesenchymal markers and an increase in epithelial markers, reminiscent of observations made in lung cancer cells." (PMID 36864480, 2023). "In addition, overexpression of ELF3 in ovarian cancer cell lines suppressed their growth." (PMID 28199976, 2017). "To further evaluate the role of ELF3 expression in EMT in ovarian cancer cells, we examined the effects of ELF3 overexpression in two ovarian cancer cell lines." (PMID 28199976, 2017). "Based on the result, we chose the ovarian cancer cell lines OVCA429 and SKOV3ipluc, which express endogenous ELF3 at low levels, for further functional studies of the roles of ELF3 on ovarian cancer pathogenesis by overexpressing ELF3 in the cell lines." (PMID 28199976, 2017). "We also chose the ovarian cancer cell lines CaOV3 and OVCA433, which have high levels of endogenous ELF3 expression, for further study by silencing ELF3 in these cell lines with small interfering RNA (siRNA)." (PMID 28199976, 2017). "Recent studies have demonstrated that KLF5 forms a transcriptional complex with EHF and ELF3, remodeling RAD51 transcription to enhance the homologous recombination repair (HRR) pathway in ovarian cancer cells, thereby promoting ovarian cancer progression and PARPi resistance." (PMID 40307891, 2025). "Furthermore, in the CCLE database, the expression levels of BUB1B, NDC80, ELF3, TFAP2A and hsa-miR-655 were confirmed among different ovarian cancer cell lines." (PMID 33493131, 2021). "We also chose two EHF-like family members (ELF-3 and ELF-5), which has been reported to be involved in ovarian cancer, to detect whether they can regulate LAIR promoter activity." (PMID 29915163, 2018). "ELF3-overexpressing OVCA429 and SKOV3ipluc cells exhibited 46% (p < 0.001) and 25% (p < 0.001) lower rates of cell proliferation, respectively, than did mock-transfected ovarian cancer cells." (PMID 28199976, 2017). "Downregulation of ELF3 expression in high-grade ovarian tumors results in enhanced EMT, which may lead to the development of ovarian cancer with an increasingly aggressive phenotype and, subsequently, poor survival." (PMID 28199976, 2017). "Furthermore, delineation of the molecular mechanism of ELF3-mediated EMT will provide insight into the roles of this epithelial-restricted Ets transcription factor in ovarian surface epithelium differentiation and ovarian cancer pathogenesis." (PMID 28199976, 2017). "Furthermore, upregulation of ELF3 increased expression of epithelial markers, decreased expression of mesenchymal markers, and mediated translocation of epithelial-mesenchymal transition (EMT) signaling molecules in ovarian cancer cells." (PMID 28199976, 2017).
ovarian carcinoma (continued). "Interestingly, a recent study showed that KLF5 forms a transcriptional complex with EHF and ELF3 and binds to the promoter region of RAD51 to enhance its transcription, strengthening the homologous recombination repair pathway and consequently inducing chemoresistance in ovarian cancer cells." (PMID 39865088, 2025). "However, another EMT regulator ELF3, when up-regulated, could mediate the EMT signal molecules cascade to increase the expression of epithelial markers and decrease the mesenchymal markers in ovarian cancer." (PMID 33493131, 2021).
osteoarthritis (6 papers, 2018 to 2023). A noninflammatory degenerative joint disease occurring chiefly in older persons, characterized by degeneration of the articular cartilage, hypertrophy of bone at the margins and changes in the synovial membrane. "Conditional deletion of Elf3 in mouse chondrocytes results in decreased IL-1β-mediated induction of Mmp13 and Nos2, and these mice undergo less cartilage loss in a model of osteoarthritis." (PMID 30200227, 2018). "Elevated Bone marrow mesenchymal stem cell-derived exosomal miR-206 promotes the proliferation and differentiation of osteoblasts in osteoarthritis and inhibits apoptosis by reducing Elf3." (PMID 36409439, 2023). "Recently, a role for ELF3 in contributing to cartilage degradation was demonstrated in a model of post-traumatic osteoarthritis." (PMID 30200227, 2018). "ELF3 levels are elevated in human cartilage from patients with osteoarthritis (OA), and ELF3 contributes to the IL-1β-induced expression of genes encoding Mmp13, Nos2, and Ptgs2/Cox2 in chondrocytes in vitro." (PMID 29691435, 2018). "ELF3 protein is overexpressed in the cartilage of patients with osteoarthritis, and drives expression of the IL-1β-induced genes MMP13, NOS2, and PTGS2/COX2 in chondrocytes." (PMID 30200227, 2018). "Moreover, it has been shown that EXOs derived from MSCs overexpressing miR-212 were found to target ELF3 and suppress chondrocyte degeneration and inflammation in primary cells derived from patients with osteoarthritis." (PMID 37626949, 2023). "The role of miR‐206 and E74‐like factor 3 (Elf3) has been identified in osteoarthritis (OA), while the effect of exosomal miR‐206 from bone marrow mesenchymal stem cells (BMSCs) in OA remains largely unknown." (PMID 34160894, 2021).
ampullary carcinoma (5 papers, 2017 to 2023). "A number of mutations in ELF3 were identified in ampullary carcinoma by next generation sequencing analysis, many of which occur in the ESE domain, referred to as a hotspot region." (PMID 33712555, 2021). "Inactivating mutations in ELF3 occur in ~6% of cholangiocarcinomas and gallbladder cancers, and in ~10% of ampullary cancers, which arise from the Ampulla of Vater, the nipple-like projection into the duodenum into which the pancreatic and bile ducts open." (PMID 30200227, 2018). "Ampullary cancers originate from the different epithelial cell types present at the site, and ELF3 mutations occur in both intestinal-type and pancreatobiliary-type ampullary adenocarcinomas." (PMID 30200227, 2018). "Interestingly, five patients had inactivating ELF3 mutations, a driver of ampullary carcinoma." (PMID 36999792, 2023).
biliary tract cancer (5 papers, 2018 to 2024). "The majority of ELF3 truncating mutations in biliary tract cancer are heterozygous, suggesting ELF3 may act as a haplo-insufficient tumour suppressor." (PMID 30200227, 2018). "Conditioned medium from biliary tract cancer cells overexpressing ELF3 enhanced the migration of natural killer cells and CD8+ T cells toward the conditioned medium." (PMID 39219440, 2024). "Similarly, knockdown of ELF3 in biliary tract cancer cells resulted in upregulation of mesenchymal markers such as ZEB1/2, VIM and TWIST1 accompanied by the downregulation of KRT19." (PMID 36864480, 2023).
cervical cancer (5 papers, 2022 to 2025). A primary or metastatic malignant neoplasm involving the cervix. "TCGA analyses demonstrated that high ELF3 expression levels were associated with HPV+ head and neck cancers regardless of the subsite, and co-occurring HIDDEN cell biomarkers were preliminarily associated with worse outcomes in cervical cancer." (PMID 37031202, 2023).
Hyperglycemia (5 papers, 2020 to 2025). An increased concentration of glucose in the blood. "Hyperglycemia enhances pyroptotic signaling by upregulating E74-like factor 3 (ELF3) and downregulating histone methyltransferase SET8 expression." (PMID 40978461, 2025). "Specificity protein 1 (SP1) has been reported to modulate ELF3 expression and influence hyperglycemia-induced COX2 and iNOS expressions in endothelial cells." (PMID 35607962, 2022). "Hyperglycemia, via upregulation of E74-like ETS transcription factor 3 (ELF3), induces cyclooxygenase 2 (COX2) and inducible nitric oxide synthase (iNOS) expressions, thus leading to endothelial apoptosis and vascular endothelial injury." (PMID 35607962, 2022). "Furthermore, hyperglycemia induce upregulation of E74-like ETS transcription factor 3 (ELF3), leading to NLRP3 inflammasome activation." (PMID 35844498, 2022). "As ELF3 is an inducer of endothelial inflammation, ELF3 inhibition may become a crucial strategy for the treatment of hyperglycaemia-mediated endothelial inflammation and injury." (PMID 32439949, 2020). "In conclusion, ELF3 interacted with SET8 to modulate MARK4 expression, which participated in hyperglycaemia-mediated endothelial NLRP3 inflammasome activation." (PMID 32439949, 2020). "In the present study, we hypothesized that ELF3 may increase MARK4 expression, thus playing a crucial role in hyperglycaemia-induced NLRP3 inflammasome activation in vascular endothelial cells." (PMID 32439949, 2020).
nasopharyngeal carcinoma (5 papers, 2019 to 2024). A carcinoma arising from the nasopharyngeal epithelium. "ELF3 is identified to direct target miR-212 to suppress nasopharyngeal carcinoma cells proliferation." (PMID 35284413, 2022). "A recent study had reported that activation of ELF3 gene expression by CircHIPK3 promotes proliferation and invasion in nasopharyngeal carcinoma which affect the prognosis of patients." (PMID 30832724, 2019). "Besides, E74-like ETS transcription factor 3 (ELF3) expression was upregulated by circHIPK3 via sponging miR-4288, therefore enhancing the malignant phenotype and exerting oncogenic effects in nasopharyngeal carcinoma." (PMID 36606192, 2022). "CircHIPK3 was highly expressed in nasopharyngeal carcinoma (NPC), and represses NPC development via sponging miR-4288 to promote ELF3 expression." (PMID 39519039, 2024). "NEW & NOTEWORTHY We identified the functions of E74-like factor 3 (ELF3) in glycolysis and immune escape of nasopharyngeal carcinoma cells for the first time." (PMID 39219440, 2024). "As a transcription factor, ELF3 promoted mucin-16 (MUC16) expression by binding to its promoter, leading to the glycolysis-mediated immune escape of nasopharyngeal carcinoma (NPC) cells." (PMID 39219440, 2024).
Arrhythmia (4 papers, 2014 to 2024). Any cardiac rhythm other than the normal sinus rhythm. "Under continuous light and in darkness, it has been reported that elf3 loss-of-function alleles display arrhythmia." (PMID 24867215, 2014). "Loss of ELF3 activity leads to arrhythmia and loss of gating of environmental signals under short T-cycles." (PMID 25147271, 2014). "In contrast to the observation that ELF3 dysfunction results in clock arrhythmia in Arabidopsis, the circadian clock is conserved in soybean regardless of the functional status of J/GmELF3a." (PMID 34246232, 2021). "As these null elf3 studies were conducted in the context of arrhythmia, placing ELF3 in the clock network has been difficult." (PMID 24867215, 2014).
breast tumors (4 papers, 2006 to 2026). "In both clinical databases, ELF3 expression is significantly higher in BRCA1-associated breast tumors than in non-BRCA1-associated breast tumors." (PMID 41498327, 2026). "Specifically, ELF3 was annotated as a cancer gene for rectum adenocarcinoma, colorectal neoplasms, hematologic diseases and breast neoplasms in the database of DriverDB, CoReCG, and DDMGD respectively." (PMID 32064261, 2020). "CDH1 and ELF3 were expressed at a significantly higher level in cells with an epithelial morphology, whereas FN1, FOSL1, VIM, ZFHX1B, SNAI2, SERPINE1 and TFGB1 showed a higher expression in fibroblastic breast tumour cells." (PMID 16495925, 2006).
melanoma (4 papers, 2020 to 2025). A malignant, usually aggressive tumor composed of atypical, neoplastic melanocytes. "While previous studies have investigated m6A modifications in melanoma, the specific biological role of ELF3 as an m6A “reader” in SKCM remains poorly understood." (PMID 40867324, 2025). "YTHDF1 and HNRNPA2B1 were significantly over-expressed in patients with melanoma while ELF3 was down-regulated." (PMID 32549786, 2020). "In particular, ELK3, ETS1, ETV1, ETV4, ETV5, and SPI1 were significantly upregulated in melanoma, whereas EHF, ELF3, ELF5, ERG, ETS2, ETV7, and SPDEF were significantly downregulated in the tumor." (PMID 33424867, 2020). "In addition, no studies have reported on the expression and function of ELK3, ETV5 ELF3, ELF5, ETS2, and SPDEF in melanoma." (PMID 33424867, 2020). "Interestingly, although the role of ELF3 in melanoma has not yet been examined, previous studies have reported observing a significant downregulation of ELF3 in melanoma tumors, suggesting that expression of ELF3 may aid the regulation of melanoma growth and development." (PMID 40699755, 2025).
ovarian tumours (4 papers, 2017 to 2024). "Immunolocalization of ELF3 and E-cadherin on paraffin-embedded ovarian tumor tissue sections confirmed the positive correlation between ELF3 and E-cadherin protein expression (R = 0.456, p = 0.008)." (PMID 28199976, 2017). "Also, ovarian tumor progression is suppressed by ELF3 overexpression in animal models." (PMID 28199976, 2017). "Because EMT has been associated with tumor progression, we evaluated whether expression of ELF3 was associated with that of the known EMT markers, including Snail, E-cadherin, β-catenin, and β-catenin–interacting protein 1 in 108 microdissected ovarian tumor samples." (PMID 28199976, 2017). "Conversely, ELF3 knockdown in OC cell lines induced epithelial to mesenchymal transition (EMT), suggesting ELF3 inhibits ovarian tumour progression by maintaining the epithelial state." (PMID 30200227, 2018).
pancreatic cancer (4 papers, 2019 to 2023). "In metastatic lymph nodes from lung, breast and pancreas cancers, the upregulation of Ets family transcription factor Esx/Elf3 in metastatic lymph nodes correlated well with expression of EpCAM." (PMID 31225512, 2019).
squamous cell carcinoma (4 papers, 2016 to 2022). A carcinoma arising from squamous epithelial cells. "They found novel somatic mutations in the MAPK1 gene (8%), HLA-B gene (9%), EP300 (16%), FBXW7 (15%), NFE2L2 (4%), and ERBB2 (6%) of 79 squamous carcinomas, and ELF3 (13%) and CBFB (8%) mutations in 24 adenocarcinomas." (PMID 26701206, 2016). "FOXO1 was most strongly associated with sarcoma (DOID:1115, with ELF1), and squamous cell carcinoma (DOID:5520, with ELF3) (k-mer = WAAACAGGAAG for both terms; mean k-mers Z-score > 5)." (PMID 31913281, 2020).
cervical adenocarcinoma (3 papers, 2018 to 2024). An adenocarcinoma arising from the cervical epithelium. "Frameshift mutations in ELF3 occur in ~13% of cervical adenocarcinomas, which surprisingly express higher levels of ELF3 mRNA compared to wild-type tumours." (PMID 30200227, 2018).
colorectal adenocarcinoma (3 papers, 2019 to 2023). The most common type of colorectal carcinoma. "Analysis of ELF3 in colorectal adenocarcinoma (CRC) tissue microarray panels indicates that ELF3 expression is significantly decreased in colorectal tumour tissues and that the presence of ELF3 expression correlates positively with better clinical prognosis." (PMID 30148686, 2019). "In addition, we found that three (CDX1, CDX2, and KLF4) of the four transcription genes (CDX2, KLF4, CDX1, and ELF3) with low expression in CSCC also showed low expression in colorectal adenocarcinoma, while ELF3 achieved the opposite result in colorectal adenocarcinoma." (PMID 35194959, 2022).
diabetes mellitus (3 papers, 2019 to 2025). A metabolic disorder characterized by abnormally high blood sugar levels due to diminished production of insulin or insulin resistance/desensitization. "Elf3 serves as a highly specific marker for DKD as it is only found in the exosomes of patients with diabetes mellitus patients who have developed DKD." (PMID 39941397, 2025). "Therefore, ectopic expression of Elf3 in podocytes may be involved in the induction of abnormal signaling, including RII-Smad3 axis, leading to glomerulosclerosis in diabetes mellitus." (PMID 31150422, 2019).
pancreatic adenocarcinoma (3 papers, 2023 to 2025). "Several GEO databases of pancreatic adenocarcinoma revealed a positive correlation of ELF3 with Notch-3 and -4 transcripts." (PMID 37308977, 2023). "This is interesting since a previous study reported that Elf3 expression levels increase during pancreatic development from embryonic days E12.5 to E18.5 in mice, and elf3 mediates epithelial identity genes in a pancreatic adenocarcinoma cell line." (PMID 41147741, 2025).
prostate tumors (3 papers, 2010 to 2022). "Bioinformatic analysis of two independent data sets also found increased ELF3 expression in metastatic tumours compared with primary prostate tumours, indicating that ELF3 expression may be associated with more advanced tumours." (PMID 35472129, 2022). "Increased ELF3 expression in more advanced prostate tumours was shown by immunostaining of tissue microarrays and from analysis of gene expression and genetic alteration studies." (PMID 35472129, 2022). "Additionally, there may be a subset of higher grade prostate tumours (Gleason ≥ 7) which then re‐express ELF3." (PMID 35472129, 2022).
serous ovarian cancer (3 papers, 2017 to 2023). "In high-grade serous ovarian cancer (HGSOC), ELF3 forms a positive feedback loop with LGR4, which is involved in stem-cell renewal." (PMID 36864480, 2023). "ELF3 knockdown reduced SOX2 and POU5F1/OCT4 expression, whereas overexpression of ELF3 increased SOX2 and POU5F1 expression in high-grade serous ovarian cancer cells." (PMID 36289818, 2022).
thyroid cancer (3 papers, 2022 to 2024). "Silencing of ELF3 with siRNA repressed the growth, clone formation, migration, and invasion of thyroid cancer cells by regulating the transcription of the human epidermal growth factor receptor 2 family of receptors." (PMID 39219440, 2024). "In particular, HNRNPC, RBM15B, IGFBP2, and ELF3 were upregulated, while the other 12 genes were downregulated in thyroid cancer tissues." (PMID 36389678, 2022).
ampullary adenocarcinoma (2 papers, 2019 to 2021). "Especially, an insertion was found at position 288 where a missense mutation (A332P) was detected in ELF3 in ampullary adenocarcinomas." (PMID 33712555, 2021).